L3MBTL2 (L3MBTL histone methyl-lysine binding protein 2)
Description:
Putative Polycomb group (PcG) protein. PcG proteins maintain the transcriptionally repressive state of genes, probably via a modification of chromatin, rendering it heritably changed in its expressibility. Its association with a chromatin-remodeling complex suggests that it may contribute to prevent expression of genes that trigger the cell into mitosis. Binds to monomethylated and dimethylated 'Lys-20' on histone H4. Binds histone H3 peptides that are monomethylated or dimethylated on 'Lys-4', 'Lys-9' or 'Lys-27'.
Synonyms: H-l(3)mbt-l; DKFZP761I141; dJ756G23.3; L3MBT
Tractability: Small molecule: a structure with a bound ligand is known; it has a high-quality binding pocket. PROTAC: UniProt records ubiquitination sites on it; ubiquitination databases record sites on it; its protein half-life has been measured.
Gene: Protein-coding gene on chromosome 22 (41,205,282 to 41,231,273, forward strand). Ensembl gene ENSG00000100395.
Subcellular location: Nucleus
Subcellular location (Human Protein Atlas): Nucleoplasm
Pathways (Reactome):
Gene expression (Transcription): Transcriptional Regulation by E2F6
Metabolism of proteins: SUMOylation of chromatin organization proteins
Gene Ontology:
Molecular function: histone binding; histone H4K20me1 reader activity; histone H4K20me2 reader activity; protein binding; chromatin binding; promoter-specific chromatin binding; zinc ion binding
Biological process: heterochromatin formation; negative regulation of DNA-templated transcription; regulation of DNA-templated transcription
Cellular component: nucleus; chromatin; nucleoplasm; PRC1 complex
Genetic constraint (gnomAD): Loss-of-function variants: 43 observed, 85.42 expected, observed/expected ratio (o/e) 0.5, 90% interval 0.39 to 0.65. The upper end of that interval is the gene's LOEUF score, 0.65, which puts it in group 2 of 6, group 1 being the genes least tolerant of losing a copy. Missense variants: 746 observed, 951.05 expected, observed/expected ratio (o/e) 0.78, 90% interval 0.74 to 0.83. Synonymous variants: 335 observed, 363.42 expected, observed/expected ratio (o/e) 0.92, 90% interval 0.84 to 1.01.
Homologues: Orthologues: chimpanzee L3MBTL2 (99% identical), pig L3MBTL2 (96% identical), rabbit L3MBTL2 (96% identical), guinea pig L3MBTL2 (95% identical), dog L3MBTL2 (93% identical), rat L3mbtl2 (91% identical), mouse L3mbtl2 (91% identical), macaque L3MBTL2 (76% identical), tropical clawed frog l3mbtl2 (65% identical), zebrafish l3mbtl2 (52% identical). Paralogues in human: MBTD1 (48% identical), L3MBTL1 (16% identical), SFMBT2 (16% identical), L3MBTL3 (16% identical), SCMH1 (16% identical), L3MBTL4 (15% identical), SFMBT1 (15% identical), SCML2 (15% identical), PHC1 (10% identical), PHC2 (10% identical), PHC3 (9% identical), SAMD11 (8% identical), and 6 more.
Diseases named in the same sentence as L3MBTL2 in open-access papers:
L3MBTL2 is named in the same sentence as 25 diseases in open-access papers, as found by Europe PMC text mining. Sharing a sentence is not in itself a finding about the gene and the disease. The quoted sentences say what the papers report.
medulloblastoma (3 papers, 2010 to 2024). A malignant, invasive embryonal neoplasm arising from the cerebellum. "It will be important to determine whether the role of LIN-61 in DSB repair is conserved in human MBT proteins and whether MBT mutated tumours, such as medulloblastomas with mutations in L3MBTL2, L3MBTL3 or SCML2, are HR deficient as they too may prove responsive to treatment with PARP inhibitors." (PMID 23505385, 2013). "Single- and double-strand deletions of L3MBTL2 and L3MBTL3 were found in medulloblastoma whereas L3MBTL4 has mutations or deletions in breast cancer." (PMID 39231972, 2024). "A recent study reported focal hemi- and homozygous deletions of L3MBTL2 and L3MBTL3 in medulloblastoma." (PMID 20698951, 2010).
breast carcinoma (2 papers, 2022 to 2024). "Data from the GEPIA database indicated that L3MBTL2 mRNA levels are significantly upregulated in various types of cancers, including lung cancer, liver cancer, breast cancer, skin cutaneous melanoma, and stomach adenocarcinoma." (PMID 35521536, 2022).
liver cancer (2 papers, 2022 to 2025). An epithelial or non-epithelial malignant neoplasm that arises from the liver. "ATO exerts anti-osteosarcoma effects by inhibiting UBE2O-mediated L3MBTL2 degradation, while arborinine blocks UBE2O’s degradation of substrates like AMPKα2 and demonstrates synergistic chemotherapeutic potential in breast and liver cancer models." (PMID 40426910, 2025).
lung carcinoma (2 papers, 2021 to 2022). "MGA loss was accompanied by a decrease in L3MBTL2 levels, as we had observed in our lung cancer models." (PMID 34236315, 2021).
malignant brain tumor (2 papers, 2018 to 2023). "The malignant brain tumor (MBT) family is a large family with L3MBTL1, L3MBTL2, L3MBTL3, L3MBTL4, and other members." (PMID 38201555, 2023).
pancreatic cancer (2 papers, 2022 to 2025). "Our study shows for the first time that L3MBTL2 functions as an oncogene, significantly promoting cell proliferation, migration, invasion, and tumorigenesis in pancreatic cancer." (PMID 35521536, 2022). "To further verify the L3MBTL2 expression level in PDAC, we selected three pancreatic cancer cell lines (ASPC-1, BXPC-3, and PANC-1) and one pancreatic ductal epithelial cell line (HPDE6-C7)." (PMID 35521536, 2022). "In summary, these results reveal that the oncogenic function of L3MBTL2 in pancreatic cancer is closely related to its negative regulatory effect on CGA, which plays a tumor suppressor role in PDAC." (PMID 35521536, 2022).
schizophrenia (2 papers, 2022 to 2024). A major psychotic disorder characterized by abnormalities in the perception or expression of reality. "There is evidence that variants in L3MBTL2 affect early embryonic development and that schizophrenia is associated with early neurodevelopmental disorders." (PMID 40226707, 2024). "For example, L3MBTL2 is a transcriptional repressor expressed in adipose, brain, heart, lung, and muscle; and was very recently implicated in migraine, schizophrenia, and depression via cross-trait genetic analysis." (PMID 36292730, 2022).
brain Tumors (1 paper, 2024). "Besides, five additional inputs were found after searching for alterations in BCOR, BCORL1, EP300, TRAP1, CREBBP, and L3MBTL2 in the repository of 23 published studies on neuroepithelial brain Tumors including 7207 samples of 6761 patients." (PMID 38637838, 2024).
breast tumor (1 paper, 2010). "L3MBTL1, L3MBTL2 and L3MBTL3 paralogs were not targeted by deletion in our breast tumor set." (PMID 20698951, 2010).
non-small cell lung carcinoma (1 paper, 2021). A group of at least three distinct histological types of lung cancer, including non-small cell squamous cell carcinoma, adenocarcinoma, and large cell carcinoma. "We further confirmed decreased E2F6, L3MBTL2, and PCGF6 protein levels in MGA mutant human non-small cell lung cancer lines H2291 and Lou-NH-91 when compared to wild-type lines such as NCI-H1975, NCI-H23, and 91T." (PMID 34236315, 2021).
osteosarcoma (1 paper, 2025). A usually aggressive malignant bone-forming mesenchymal neoplasm, predominantly affecting adolescents and young adults. "In summary, UBE2O promotes osteosarcoma progression by degrading L3MBTL2, disrupting its nuclear condensates, derepressing IFIT2 transcription, and activating the TNF/NF-κB pathway." (PMID 40426910, 2025). "The degradation of L3MBTL2 leads to elevated IFIT2 expression, which is upregulated in osteosarcoma and correlates with tumor progression and poor prognosis." (PMID 40426910, 2025). "By stabilizing L3MBTL2, ATO suppresses IFIT2 gene expression, ultimately inhibiting osteosarcoma cell proliferation and tumor growth." (PMID 40426910, 2025). "UBE2O exhibits a negative correlation with L3MBTL2 in osteosarcoma, and its high expression predicts poor prognosis." (PMID 40426910, 2025).
pancreatic adenocarcinoma (1 paper, 2022). "According to the TCGA and GTEx database, L3MBTL2 expression was preferentially higher in pancreatic adenocarcinoma (PAAD) tissues (n = 179) than in nontumor tissues (n = 171)." (PMID 35521536, 2022).
Sepsis (1 paper, 2025). Sepsis is defined as life-threatening organ dysfunction caused by a dysregulated host response to infection. "A total of six hub genes (RORA, L3MBTL2, PHC1, RPA1, CHD3, and RANGAP1) associated with SUMOylation was identified in sepsis in the current study." (PMID 40274894, 2025). "Although no research has directly linked L3MBTL2 to sepsis, numerous studies have highlighted its unique oncogenic role in tumor development." (PMID 40274894, 2025). "Aflatoxin B1 was identified as a prospective therapeutic agent for sepsis based on CHD3, L3MBTL2, PHC1, RANGAP1, and RORA." (PMID 40274894, 2025). "L3MBTL2, RPA1, and RANGAP1 have not been previously associated with sepsis, offering new avenues to explore their roles." (PMID 40274894, 2025). "This study shows that hub genes (RORA, L3MBTL2, PHC1, RPA1, CHD3, and RANGAP1) may distinguish controls and diseases to facilitate diagnosis of sepsis." (PMID 40274894, 2025).
tumor (7 papers, 2013 to 2025). "Functional validation revealed tumor-suppressive roles of L3MBTL2 and VHL, highlighting their potential as therapeutic targets in STAD." (PMID 40821814, 2025). "The tumor weight and volume of the L3MBTL2 overexpression group were significantly increased, whereas L3MBTL2 knockdown had the opposite effect." (PMID 35521536, 2022). "We first investigated the role of L3MBTL2 in PDAC, because the expression level of L3MBTL2 shows a greater discrepancy between tumor and adjacent tissues in PDAC than in other cancers." (PMID 35521536, 2022). "We also investigated the effects of L3MBTL2 in liver (HepG2) and lung (H1299) cancer cells, indicating a critical oncogenic role for L3MBTL2 in tumor initiation and progression." (PMID 35521536, 2022). "In summary, our study revealed a distinct oncogenic role of L3MBTL2 in tumor development and an L3MBTL2-mediated transcriptional repression mechanism." (PMID 35521536, 2022). "To begin to examine the role of ncPRC1.6 complex subunits in regulation of gene expression by MGA, we employed Crispr Cas9 to individually inactivate L3mbtl2, Pcgf6, or Mga in the mouse tumor derived KP cells." (PMID 34236315, 2021). "MGA, MAX, E2F6, and L3MBTL2 were seen to bind several thousand promoters in MGA-expressing KP tumor cells suggesting that the PRC1.6 complex plays a broad role in tumor cell gene expression." (PMID 34236315, 2021). "Tumor cells with BRAFV600E mutation from PT and LM all highly expressed VPS13B, a gene that may function in vesicle-mediated transport, and L3MBTL2, a gene that may inhibit cell divisions." (PMID 35974387, 2022). "Here, we found that L3MBTL2 plays a distinct oncogenic role in tumor development." (PMID 35521536, 2022). "This suggests that L3MBTL2 plays a critical role in cancer, and the abnormal expression of L3MBTL2 may be involved in multiple mechanisms of tumor development." (PMID 35521536, 2022). "In this study, we examined the contribution of L3MBTL2 to tumor progression." (PMID 35521536, 2022). "The link between ncPRC1.6 activity and the effects of MGA loss on specific gene expression was further investigated by comparing gene expression profiles of Crispr-mediated deletion of Mga with deletions of ncPRC1.6 subunits Pcgf6 and L3mbtl2 in KP tumor cells." (PMID 34236315, 2021). "Therefore, we assumed that the target gene of L3MBTL2 might be a tumor suppressor gene with a certain role in cancer." (PMID 35521536, 2022). "Simultaneously, we found that the tumor-promoting capacity of L3MBTL2 could be markedly abolished by CGA overexpression, whereas the loss of CGA could also rescued the antitumor effect of L3MBTL2 knockdown." (PMID 35521536, 2022). "By degrading L3MBTL2, UBE2O depletes this tumor suppressor protein, thereby compromising its tumor-suppressive function." (PMID 40426910, 2025). "Functional validation of key SRGs, including L3MBTL2 and VHL, confirmed their tumor-suppressive roles." (PMID 40821814, 2025). "(I) Proposed mechanism of MGA mediated tumor suppressive effects: MGA acts as a scaffold and stabilizes atypical PRC1.6 members, including L3MBTL2." (PMID 34236315, 2021). "We determined MAX, MGA, MYC, L3MBTL2, E2F6, and RNA polymerase II (RNA pol2, all phosphorylated forms) occupancy in Mga-inactivated and control (empty) KP tumor-derived cells lines." (PMID 34236315, 2021). "More importantly, we found that BRAFV600E tumor cells highly expressed L3MBTL2 whereas BRAFWT tumor cells did not, which is further verified in TCGA-COAD database." (PMID 35974387, 2022). "In addition, we demonstrated CGA acts as a tumor suppressor gene in PDAC and verified that the oncogenic function of L3MBTL2 is closely related to its regulatory effect on CGA." (PMID 35521536, 2022).
cancer (4 papers, 2015 to 2023). A tumor composed of atypical neoplastic, often pleomorphic cells that invade other tissues. "To explore the function of L3MBTL2 in other cancers, we established L3MBTL2 knockdown stably transfected H1299 and HepG2 cell lines." (PMID 35521536, 2022). "Interestingly, very recent studies showed that MGA, L3MBTL2 and PCGF6 are also destabilized upon USP7 inactivation in human cancer cell lines, indicating conserved USP7 function through mammalian evolution." (PMID 36772830, 2023). "However, we found that among the DEGs, one of the genes most strongly upregulated in response to L3MBTL2 knockdown was a hormone-related gene (CGA), whose role in cancer is still unclear." (PMID 35521536, 2022). "However, the other biological functions of L3MBTL2 are largely undefined, and there is no direct evidence that L3MBTL2 plays a role in cancer." (PMID 35521536, 2022).
L3MBTL2 also shares sentences with these, for which no sentence is quoted: acute lymphoblastic leukemia (1 paper); anaplastic astrocytoma (1); depression (1); glioma (1); leukemia (1); migraine (1); neurodevelopmental disorder (1); skin cutaneous melanoma (1); stomach adenocarcinoma (1); T-cell acute lymphoblastic leukemia (1).